SOX2 (SRY-box transcription factor 2)
Diseases named in the same sentence as SOX2 in open-access papers (continued):
Sharing a sentence is not in itself a finding about the gene and the disease.
breast cancer (continued). "Inhibition of SOX2 expression has been shown to suppress cancer initiation and tumour cell proliferation, migration, invasion, and metastasis as well as to induce apoptosis in oligodendroglioma, lung cancer, breast cancer, and osteosarcoma cells." (PMID 29666462, 2018). "Sox2 expression is furthermore a resistance marker for paclitaxel and tamoxifen in breast cancer." (PMID 30388742, 2018). "In addition, single-cell gene expression profiling as well as a Sox2 reporter breast cancer cell line were used to validate the role of dedifferentiation mediated by progranulin." (PMID 30454027, 2018). "IL-1RA added to the coculturing system partially blocked the upregulation of tumor-associated pluripotency factors Sox2 and KLF4 in both breast cancer cells and ovarian cancer cells, which verified the role of IL-1β in the promotion of stem cell-like properties." (PMID 29670904, 2018). "Interestingly, the ectopic expression of the overlapping transcript leads to a massive increase in SOX2 expression levels, suggesting it plays a key role in the maintenance of SOX2 expression in breast carcinoma." (PMID 29732012, 2018). "Sox2 upregulation by VEGFA mediates the loss of miR-452, and miR-452 loss is required for Slug upregulation and for VEGFA-driven cell motility, invasion and metastasis in breast cancer models." (PMID 28504716, 2017). "Inhibitors of Notch signaling (e.g. γ-secretase inhibitor) could partially suppress the function of reprogramming factors (Sox-2, Oct-4, Nanog, etc) involved in the formation of iBCSCs, and enhanced the radiation sensitivity of breast cancer cells." (PMID 28038467, 2017). "We found that SOX2 knockdown leads to decreased levels of miR-181a-5p and miR-30e-5p accompanied by decreased cell proliferation, suggesting that these two microRNAs are required for the proliferation of breast cancer cells." (PMID 28288641, 2017). "Therefore we demonstrate here a clinically relevant axis which involves SOX2/miRNAs/TUSC3 in breast cancer development." (PMID 28288641, 2017). "Importantly, inversed expression of SOX2 and TUSC3 is associated with poor prognosis of a subpopulation of breast cancer patients." (PMID 28288641, 2017). "Overexpression of SOX2 in tumors has been correlated with increased tumor thickness and invasion, metastasis in esophageal cancer, drug resistance, and decreased survival in tumors such as breast cancer and lung adenocarcinoma." (PMID 28321397, 2017). "Research has shown that the expression of Sox-2 in early stage of breast cancers." (PMID 28088791, 2017). "In breast cancer, the expression of leptin receptor is highly upregulated in tumor tissue, particularly in the CSC subpopulation, as driven by the self-renewal associated transcription factors OCT-4 and SOX-2." (PMID 28337221, 2017). "High levels of SOX2 protein are correlated with increased dissemination of breast cancer." (PMID 28288641, 2017). "In this study we examined the molecular mechanisms used by SOX2 in the proliferation and migration of breast cancer cell lines and identified that SOX2 regulates two miRNAs (miR-181a-5p and miR30e-5p) which in turn influence the expression of a common downstream target TUSC3." (PMID 28288641, 2017). "High levels of SOX2 have been found in metastasized breast cancer nodules." (PMID 28288641, 2017). "Together these data confirm that SOX2 is required for the proliferation of breast cancer cells." (PMID 28288641, 2017). "In this study, we found that SOX2 is also required for the proliferation of breast cancer cells." (PMID 28288641, 2017). "In a murine model of breast cancer, TAMs are also demonstrated to promote CSC phenotypes in breast cancer cells through the EGF-mediated STAT3/SOX-2 cascade, and this cross talk could be abrogated by small molecule inhibitors against EGFR or STAT3." (PMID 28337221, 2017). "shRNA-mediated knockdown of SOX2 inhibits breast cancer cell expansion and migration." (PMID 28288641, 2017).
breast cancer (continued). "Overexpression of lncRNA-Hh in breast cancer cells increases Hh signaling accompanied by elevated levels of SOX2 and OCT4 via targeting to GAS1 (growth arrest specific 1), and consequently contributes to activation of EMT, CSC maintenance and tumorigenesis of breast cancer cells." (PMID 28872613, 2017). "Our in vitro results show that SOX2 knockdown reduces the migration of breast cancer cell lines." (PMID 28288641, 2017). "We showed that SOX2 regulates the proliferation, migration and seeding of breast cancer cells." (PMID 28288641, 2017). "For example, repression of SOX2 was found to induce cell apoptosis via cleavage of caspase-3 and activation of specific pro-apoptotic factors, and inhibit G1/S transition by regulating cyclin E in prostate cancer and cyclin D1 in breast cancer." (PMID 26969300, 2016). "Our results showed that the reduction of SOX2 in KDM2A-depleted breast cancer cells could be fully rescued by ectopic expression of JAG1 suggesting the involvement of NOTCH signaling in the regulation of SOX2 transcription." (PMID 27029061, 2016). "Together with the current findings, we postulated that FGFR1 expression could regulate SOX2 expression and subsequently neuroendocrine differentiation in breast cancer." (PMID 26673008, 2016). "In breast cancer, expression of SOX2 was detected in early stage tumors." (PMID 27029061, 2016). "Furthermore, an EGFR/STAT3/SOX2 signaling pathway has been reported in murine breast cancer stem cells." (PMID 27225481, 2016). "In breast cancer, SOX2 silencing restores tamoxifen sensitivity." (PMID 27225481, 2016). "Tier two, characterized by high YY1 and low SOX2, is found in skin, testis and breast cancers." (PMID 27225481, 2016). "Moreover, SOX2OT and SOX2 are co-upregulated in suspension culture conditions of breast cancer cell lines which advocates the growth of cellular subpopulation with cancer stem cell-like properties." (PMID 26136768, 2015). "Additionally, we identified the molecular mechanism whereby CD44ICD regulates stemness factors such as Nanog, Sox2, and Oct4, to maintain CSCs and to contribute to the tumorigenesis of breast cancer." (PMID 25909162, 2015). "We asked if Oct4, a Sox2 co-factor in ESCs, is also expressed in these breast cancer cell lines." (PMID 25868977, 2015). "Here, we show that G9a regulates Sox2 protein stability in breast cancer cells." (PMID 26492085, 2015). "For example, SOX2 and AP2α exhibited putative two CGIs at the promoter and exon 1, and methylation at the exon 1 region has shown to be significantly correlated to its gene expression in GCs and breast cancers." (PMID 26695186, 2015). "SOX2 has been shown to be a major player in the tumorigenicity of breast cancers." (PMID 26258069, 2015). "Since Sox2 is a key player in the oncogenicity of breast cancer, we hypothesized that alteration of G9a activity would have an effect on the oncogenic characteristics of MCF7 cells, such as migration, invasion, and cancer stem cell characteristics." (PMID 26492085, 2015). "An abnormal expression of SOX2 has been identified in lung, stomach, liver and breast cancers, and in other tumors, which suggests that SOX2 may function in tumor development, invasion and metastasis." (PMID 25663891, 2015). "Interestingly, ectopic expression of G9a in ZR-75-1 cells, which like MCF7 cells are a representative ER(+) breast cancer cell line, increased Sox2 protein levels." (PMID 26492085, 2015). "Because Sox2 plays a crucial role in promoting the stem cell characteristics of breast cancer cells, we examined whether G9a activity is related to the self-renewal of MCF7 cells by analyzing their ability to form mammospheres." (PMID 26492085, 2015). "We have recently described a novel phenotypic dichotomy within estrogen receptor-positive breast cancer cells; the cell subset responsive to a Sox2 regulatory region (SRR2) reporter (RR cells) are significantly more tumorigenic than the reporter unresponsive (RU) cells." (PMID 25868977, 2015).
breast cancer (continued). "Immunopositivity for Sox2 has been documented in examples of various other cancers including, but not limited to, lung adenocarcinoma, melanoma, breast carcinomas, and prostate carcinoma." (PMID 25713758, 2015). "Moreover, even breast carcinoma cell lines with inherently low SOX2 levels as observed in 2D cultures (e.g. HS578T or MDA-MB468) are able to activate the gene dynamically when cultured under conditions that promote CSCs." (PMID 26498353, 2015). "Importantly, ectopic expression of SOX2OT led to an almost 20-fold increase in SOX2 expression, together with a reduced proliferation and increased breast cancer cell anchorage-independent growth." (PMID 25006803, 2014). "Importantly, breast cancer cells overexpressing Sox2 showed an enhanced resistance to the antiproliferative effects of tamoxifen treatment in vitro and in vivo." (PMID 24178749, 2014). "Aberrant expression of the embryonic stem cell marker Sox2 has been reported in breast cancer (BC)." (PMID 25380620, 2014). "Interestingly, Sox2 has been proposed to be a possible driver of the basal-like phenotype in sporadic breast cancer because it is expressed frequently in basal-like breast carcinomas." (PMID 24178749, 2014). "In addition, the level of Sox2 expression is strongly correlated with tumour grade in breast cancer, and high expression of Sox2 has been proposed to increase metastatic potential." (PMID 24178749, 2014). "Here, we present evidence that Sox2, a transcription factor that is key in maintaining pluripotent properties of stem cells, is a crucial player in the development of resistance to tamoxifen in ER-positive breast cancer cells." (PMID 24178749, 2014). "Other groups have reported SOX2 expression in a variety of early stage postmenopausal breast carcinomas and lymph nodes metastases, suggesting that SOX2 may play an early role in breast carcinogenesis and that high expression may promote metastatic potential." (PMID 25006803, 2014). "SOX2/CDX2 ratio had prognostic relevance in CSC-enriched breast cancers." (PMID 23982413, 2013). "Furthermore, recent studies have shown that the Sox2 protein level strongly corresponds with less differentiated basal cell-like breast carcinomas, and the Sox2 protein is frequently found to be down-regulated in gastric carcinomas." (PMID 23451179, 2013). "Sox2, an embryonic stem cell marker, is aberrantly expressed in a subset of breast cancer (BC)." (PMID 23815808, 2013). "In our study on a cohort of postmenopausal patients displaying both negative and positive lymphonodal status we could confirm the aberrant expression of SOX2 in breast cancer." (PMID 21276239, 2011). "Our study furthermore contradicts reports which show that ectopic overexpression of SOX2 enhances tumorigenicity of prostate cancer cells and of breast cancer cells but is in line with reports indicating a tumor-suppressive function of SOX2 in gastric cancer cells lines." (PMID 22070920, 2011). "In breast cancer, SOX2 expression was reported as a feature of basal-like tumors." (PMID 21276239, 2011). "Recently, the same effect after SOX2 knockdown has been reported in MCF7 breast carcinoma cells." (PMID 22070920, 2011). "Such cell type specificity in cofactors may account for some of the differences observed downstream of SOX2 activation in breast cancer and lung SCC." (PMID 20126410, 2010). "Overexpressed SOX2 may promote cell proliferation and tumorigenesis of breast cancer cells through enhancing the G1/S transition of cell cycle." (PMID 20814443, 2010). "Moreover, the expression of SOX2 is inversely correlated with the age at breast cancer diagnosis, and presents a 3.76‐fold odds ratio (OR) for the early onset of breast cancer." (PMID 40959920, 2025). "Furthermore, the link between NFIs and the SOXB1 family may also be through NFI-mediated upstream regulation of SOX2 expression, as noted in breast cancer cells, dental epithelial stem cells (DESCs), dental pulp stem cells, and bone marrow stem cells." (PMID 39617063, 2025).
breast cancer (continued). "The reduction in Nanog, SOX2, and Oct4 protein expression levels suggests that hinokitiol may inhibit the stemness properties of breast cancer cells by suppressing the key regulators of stemness and the modulation of self-renewal and differentiation in cancer progression." (PMID 38612715, 2024). "STEMVAC is a DNA plasmid-based vaccine (STEMVAC) encoding Th1 selective epitopes from five antigens associated with breast cancer stem cells (MDM2, YB1, SOX2, CDC25B, CD105) which may be beneficial in helping the body to build an effective immune response to kill tumor cells." (PMID 38255791, 2024). "Several studies demonstrated that the transcriptional activation of SOX2 is linked with tumorigenesis that leads to various cancers including glioblastoma, small cell lung cancer (SCLC), lung squamous cell carcinoma (LSCC), lung adenocarcinoma, breast cancer, and colon cancer." (PMID 39024368, 2024). "We also showed that the stemness-related transcription factors SOX2 and NANOG, in the context of the TGF-β downstream signaling cascade, are linked to NSDHL, which is consistent with TGF-β-mediated signaling to enrich and maintain the stemness of breast cancer cells." (PMID 39516821, 2024). "It has been reported that Sox2 could be m6A modified by METTL3 in the breast cancer." (PMID 36977205, 2023). "BCSCs are a small functional characteristic of breast cancer cells, which are linked with a high ability of chemoresistance and radioresistance for the aberrant expression of acetaldehyde dehydrogenase 1 (ALDH1), ATP binding cassette (ABC) transporters, sox2, oct4, and other stemness proteins." (PMID 37173892, 2023). "In addition, DDX49 may promote the growth of breast cancer stem cells by regulating the expression of Oct3/4, SOX-2 and other proteins, thus promoting the development of the disease." (PMID 37106339, 2023). "KLF4 has been shown to interact directly with Oct4 and Sox2 which are critical for somatic cell reprogramming, while in breast cancer, KLF4 may have a potent oncogenic role in tumorigenesis by maintaining stem cell-like features and by promoting cell migration and invasion." (PMID 35158755, 2022). "miR-590-5p by targeting SOX2 could inhibit breast cancer cell stemness and metastasis." (PMID 34368145, 2021). "The highly conserved residues of the C-terminal region of the HMG box can be exploited for the design of synthetic interfering peptides (iPeps) that may interfere with the function of SOX2 in breast cancer cells by competitively disrupting the cooperative interactions in the SOX2/OCT4/DNA complex." (PMID 34502261, 2021). "Furthermore, ZNF217, an m6A methyl-transferase inhibitor, inhibits the m6A modification of several pluripotency factor mRNAs, including NANOG, KLF4 and SOX2 in breast cancer to promote the CSC-like phenotype and breast cancer metastasis under hypoxic conditions." (PMID 34831207, 2021). "Furthermore, we examined whether the levels of FOXO3a, FOXM1, SOX2, and DNMT1 were associated with the survival of patients with breast cancer." (PMID 31296961, 2020). "Interestingly in immune-competent mouse models of breast cancer, regulatory T cells enhance SOX2 expression by mammary cancer cells in a paracrine manner, while Sox2-expressing tumor cells recruit Tregs through NF- κB/CCL1 [Nuclear Factor kappa B/Chemokine (C-C motif) ligand 1] signaling." (PMID 33553286, 2020). "However, high Sox2-expressing breast cancer cells derived from patients modestly differentiated into EC in vivo, which may be due to the secretion of VEGF of cancer cells in vivo." (PMID 32541667, 2020). "Furthermore, knockdown of Sox2 almost abolished Snail-induced endothelial cell generation by breast cancer cells, suggesting both Sox2-induced breast cancer cell dedifferentiation to CSCs and VEGF-induced differentiation of CSCs to EC are necessary for breast cancer cell transdifferentiation." (PMID 32541667, 2020).
breast cancer (continued). "Thus far, Twist-induced lncRNA-Hh has been characterized only in breast cancer where it directly targets growth arrest-specific 1 (GAS1) to initiate Hh signaling in breast cancer, promoting SOX2 and OCT4 expression, EMT, tumorigenesis, and cells with CSC properties." (PMID 32244924, 2020). "Next, we detected whether Sox2 promoted endothelial cell generation from breast cancer cells." (PMID 32541667, 2020). "Indeed, SOX2 is frequently gained in BRCA1 germline mutated tumors and is preferentially expressed in sporadic basal-like phenotypes having similar phenotypic and clinical characteristics to breast cancer arising in BRCA1 mutation carriers." (PMID 32191225, 2020). "Thus, FMCs were characterized by much higher Sox2 expression than reported in breast cancers." (PMID 33553286, 2020). "A physical association of Sox2 with co-activator associated arginine methyltransferase 1 (CARM1) has been reported for murine embryonal carcinoma P19 cells, and CARM1-imposed Sox2 methylation at residue Arg113 further investigated in breast carcinoma MCF7 cells." (PMID 31477842, 2020). "In mammary carcinoma and glioblastoma stem cells specifically SOX4 has been implicated as a regulator of SOX2, suggesting that the observed connectivity of this factor with PI3K/AKT signaling may also reflect an indirect regulatory circuitry further involving SOX2." (PMID 31477842, 2020). "In conclusion, these findings identify a Sox2–Sox9 network as crucial for stem/progenitor cell maintenance in the human mammary gland and warrant further research into the potential of Sox family transcription factors as therapeutic targets in certain types of breast cancer." (PMID 30622340, 2019). "Thus, it is worth exploring whether and how the Rac1/HIF-1α pathway is involved in SOX2-mediated breast cancer cell motility." (PMID 31462898, 2019). "Therefore, inhibiting AKT might provide a new way of targeting SOX2 positive breast carcinoma cells." (PMID 31731811, 2019). "In addition, SOX2 knockdown inhibits the invasion of breast cancer cells in transwell assay." (PMID 28288641, 2017). "In addition, SOX2 overexpression enables higher tumourigenesis capability of breast cancer cells." (PMID 28288641, 2017). "In the ER+ breast cancer and ALK-positive anaplastic large cell lymphoma models, Sox2 was found to be the key determinant of the SRR2 reporter activity (i.e. the RR phenotype), since siRNA knockdown of Sox2 in these cells resulted in a significant loss of cancer stemness features." (PMID 28427212, 2017). "Interestingly, Sox2ot has been shown to positively regulate the expression of Sox2 in a breast cancer cell line, suggesting that it may be a regulator of Sox2 expression in repair Schwann cells too." (PMID 28903050, 2017). "Moreover, because Sox2 is expressed preferentially in the less-differentiated basal-like breast cancer subtypes, differences in the distribution of molecular subtypes between samples may alter outcomes." (PMID 28422735, 2017). "Interestingly, high levels of SOX2 proteins have also been found in 19% of breast cancer patients." (PMID 28288641, 2017). "ER+ PgR+ Ki-67- breast cancer cells were successfully recognized as nuclei with a purple color, indicating that light-field chromogenic triple immunostaining using these chromogens is suitable for use in searching for SOX2+ (or NANOG+) HIF-1α+ RNApII-S2P-/low cells in astrocytoma tissues." (PMID 26799577, 2016). "Since monomethylated Sox2 interacts with the E3 ligase WWP2 in ESCs, thereby causing its ubiquitination and degradation, we questioned whether the activity of G9a is related to the protein stability of Sox2 in breast cancer." (PMID 26492085, 2015). "So far, our reporter has identified a minority cell population in all the primary and established breast cancer cells we have studied, suggesting that the presence of functional SOX2/OCT4 in a subpopulation of tumor cells may be a relatively widespread phenomenon." (PMID 25497455, 2015).